LIMD2 (LIM domain containing 2)
Description:
Acts as an activator of the protein-kinase ILK, thereby regulating cell motility.
Synonyms: MGC10986
Tractability: Antibody: its Gene Ontology location is reachable by antibodies, with medium confidence. PROTAC: ubiquitination databases record sites on it; its protein half-life has been measured.
Gene: Protein-coding gene on chromosome 17 (63,695,883 to 63,701,172, reverse strand). Ensembl gene ENSG00000136490.
Subcellular location: Cytoplasm; Nucleus
Subcellular location (Human Protein Atlas): Nucleoplasm; Cytosol
Gene Ontology:
Molecular function: protein binding
Cellular component: cytoplasm; cytosol; nucleoplasm; nucleus; actin cytoskeleton; plasma membrane
Genetic constraint (gnomAD): Loss-of-function variants: 11 observed, 17 expected, observed/expected ratio (o/e) 0.65, 90% interval 0.41 to 1.07. The upper end of that interval is the gene's LOEUF score, 1.07, which puts it in group 4 of 6, group 1 being the genes least tolerant of losing a copy. Missense variants: 168 observed, 168.73 expected, observed/expected ratio (o/e) 1, 90% interval 0.88 to 1.13. Synonymous variants: 60 observed, 68.3 expected, observed/expected ratio (o/e) 0.88, 90% interval 0.71 to 1.09.
Homologues: Orthologues: chimpanzee LIMD2 (100% identical), macaque LIMD2 (100% identical), dog LIMD2 (98% identical), rabbit LIMD2 (98% identical), pig LIMD2 (97% identical), mouse Limd2 (96% identical), guinea pig LIMD2 (95% identical), rat Limd2 (87% identical), tropical clawed frog limd2 (69% identical), zebrafish LIMD2 (48% identical), Caenorhabditis elegans pqn-22 (23% identical), Drosophila melanogaster Tes (18% identical), and 1 more. Paralogues in human: TES (24% identical), LMCD1 (20% identical), PRICKLE1 (19% identical).
Diseases named in the same sentence as LIMD2 in open-access papers:
LIMD2 is named in the same sentence as 22 diseases in open-access papers, as found by Europe PMC text mining. Sharing a sentence is not in itself a finding about the gene and the disease. The quoted sentences say what the papers report.
non-small cell lung carcinoma (3 papers, 2020 to 2023). A group of at least three distinct histological types of lung cancer, including non-small cell squamous cell carcinoma, adenocarcinoma, and large cell carcinoma. "It has also been demonstrated that LIMD2 levels correlated with the metastatic process in PTCs and invasiveness and poor prognosis in patients melanoma, bladder, and non-small cell lung cancer." (PMID 33238381, 2020). "Furthermore, by focusing on miR-34a, LIMD2 promotes the growth and invasive migration of non-small cell lung cancer." (PMID 37529244, 2023). "In addition, LIMD2 has been characterized as an important cancer progression regulator in melanoma, bladder cancer, non-small cell lung cancer and breast cancer." (PMID 34724866, 2021). "Also, LIMD2 promotes the proliferation and invasion of non-small cell lung cancer cells." (PMID 34724866, 2021). "Previously, LIMD2 has been found to be overexpressed in many cancer types, including PTC, bladder, melanoma, breast, and non-small cell lung cancer, while its expression is negligible in normal tissues." (PMID 33238381, 2020).
Obesity (3 papers, 2020 to 2024). Accumulation of substantial excess body fat. "We focused on the PRRC2A gene which was linked to central adiposity, insulin resistance and T2D, and the LIMD2 gene which was linked to obesity, central adiposity and T2D." (PMID 37188674, 2023). "An epigenome-wide association study on obesity identified three notable loci: cg18181703 (SOCS3), cg04502490 (ZNF771), and cg02988947 (LIMD2)." (PMID 39498440, 2024). "As the sites of methylation changes were distal to the PRRC2A and LIMD2 promoters, we used CRISPR-activation to assess whether the regulatory elements harbouring obesity-associated methylation changes were involved in target gene transcription." (PMID 37188674, 2023). "In parallel, we used targeted methylation sequencing to fine map obesity-associated DNA methylation changes in the regulatory regions flanking the sentinel sites at PRRC2A, LIMD2 and 69 additional loci (N = 43 subcutaneous and N = 46 visceral adipocyte samples)." (PMID 37188674, 2023).
lung carcinoma (2 papers, 2021). "In our study, we found that LIMD2 was upregulated in OC tissues, which was consistent with the findings in lung cancer and papillary thyroid cancer." (PMID 34724866, 2021). "Further, LIMD2 was recently identified as a miR-34a target in lung cancer, a putative tumor suppressor miRNA in neuroblastoma." (PMID 34638267, 2021).
papillary thyroid carcinoma (2 papers, 2020 to 2021). "LIMD2 regulates key steps of metastasis cascade in papillary thyroid cancer cells via MAPK crosstalk." (PMID 34724866, 2021). "It has been reported that LIMD2 was a lymph node metastasis marker for papillary thyroid carcinoma (PTC)." (PMID 34724866, 2021). "Taken together, these results strongly suggest that LIMD2 plays a role in EMT of papillary thyroid carcinomas." (PMID 33238381, 2020).
thyroid cancer (2 papers, 2020 to 2022). "High levels of LIMD2 are detected in metastatic PTC and CRISPR/Cas9 gene editing of LIMD2 in thyroid cancer cell lines BCPAP and TPC1 reduced cell invasion and modified cell polarity." (PMID 35159110, 2022). "Aiming at understanding the role of LIMD2 in the metastatic process of thyroid carcinomas, we assessed the expression of LIMD2 in thyroid cell line models for distinct cancer subtypes." (PMID 33238381, 2020). "This approach was used to investigate the role of LIMD2 in thyroid cancer metastasis." (PMID 35159110, 2022).
thyroid tumor (2 papers, 2019 to 2021). A benign or malignant neoplasm affecting the thyroid gland. "Experimental data showed that LIMD2 linked with integrin-mediated signaling to cell motility and metastatic behaviors in bladder, breast and thyroid tumors." (PMID 32047513, 2019). "LIMD2 expression levels were positively correlated with cell motility metastatic potential and grade in both fresh and archived tumors, including bladder melanoma breast and thyroid tumors." (PMID 34724866, 2021).
gastric cancer (1 paper, 2024). A primary or metastatic malignant neoplasm involving the stomach. "Similarly, our identification of microtubule-associated monooxygenase, calponin, and LIM domain containing 2 (MICAL2)_rs10831776 as risk factors is consistent with previous research showing elevated MICAL2 mRNA expression in gastric cancer tissues." (PMID 39408230, 2024).
metastatic cancer (1 paper, 2022). A carcinoma which has spread from the original site of growth to another anatomic site. "The ILK/LIMD2 complex and the regulation of ILK activity by LIMD2 suggest a potential mechanism for upregulation of ILK activity specifically in metastatic cancer cells." (PMID 35804980, 2022).
neuroblastoma (1 paper, 2021). Neuroblastoma (NB) is the most common solid, extracranial childhood tumor. "Three of those genes (CBX2, GJC1, LIMD2) are encoded on 17q, a chromosomal region invariably gained in high-risk neuroblastoma." (PMID 34638267, 2021).
ovarian carcinoma (1 paper, 2021). A malignant neoplasm originating from the surface ovarian epithelium. "In conclusion, LIMD2 promotes the proliferation and invasion of ovarian cancer in vitro and in vivo, potentially through regulating the focal adhesion signaling pathway." (PMID 34724866, 2021). "Otherwise, in oder to validate the expression of LIMD2 in ovarian cancer lines, five OC cell lines were selected." (PMID 34724866, 2021). "In the present study, we aimed to investigate the role of LIMD2 in ovarian cancer." (PMID 34724866, 2021). "LIMD2 promotes the proliferation and migration of ovarian cancer in vitro and in vivo." (PMID 34724866, 2021). "In our study, by using CCK-8 assay, transwell, wound healing assays and tumor xenograft experiments, we found that LIMD2 could promote proliferation and metastasis of ovarian cancer in vitro and vivo." (PMID 34724866, 2021). "Focal adhesion signaling pathway was regulated by LIMD2 in ovarian cancer." (PMID 34724866, 2021).
systemic lupus erythematosus (1 paper, 2021). An autoimmune multi-organ disease typically associated with vasculopathy and autoantibody production. "The results demonstrated that the ECA patients with high expression of LIMD2 showed enrichment of the following pathways: systemic lupus erythematosus, DNA replication, and T cell receptor signaling pathway." (PMID 34868263, 2021).
tumor (6 papers, 2020 to 2024). "Other examples of tobacco smoke induced tumor promoters are the microtubule associated monooxygenase, i.e., calponin and LIM domain containing 2 that functions in cytoskeletal dynamics, migration and EMT in LC." (PMID 38245882, 2024). "We found that LIMD2 silencing was associated with significant reduced levels of tumor size and tumor weight (P < 0.05)." (PMID 34724866, 2021). "In univariate Cox regression analysis, LIMD2, M stage, N stage, and tumor stage showed a strong association with OS." (PMID 34868263, 2021). "Cell counting kit-8 (CCK-8) assay, transwell, wound healing assays, and tumor xenograft experiments were used to evaluate the function of LIMD2 in vitro and vivo." (PMID 34724866, 2021). "The authors showed that LIMD2 controlled the acquisition of multiple hallmarks of tumor progression as anchorage-independent growth and increased migration of different cancer types and cell lines." (PMID 33238381, 2020). "However, A2780 cells with LIMD2 knockdown generated fewer metastatic lesions, which was supported by the collective tumor weight shown in Figures 4Gand 4 H." (PMID 34724866, 2021). "Indeed, LIMD2 is a candidate biomarker of tumor progression that could be used for PTC in liquid biopsies or novel therapeutic strategies." (PMID 33238381, 2020). "Additionally, knockdown of LIMD2 could suppresses tumor through focal adhesion pathway in OC." (PMID 34724866, 2021). "Of further interest, we found a KEOPS complex member (gm6890), implicated in homologous double-strand break repair and telomere maintenance, to be strongly upregulated during tumor formation, as well as the checkpoint adaptor Claspin (CLSPN) and three chromosome 17q loci CBX2, GJC1 and LIMD2." (PMID 34638267, 2021).
cancer (4 papers, 2020 to 2023). A tumor composed of atypical neoplastic, often pleomorphic cells that invade other tissues. "LIM structural domains have been shown to be key molecules in various human cancers, and it has recently been established that LIMD2, a member of the LIMD family, is linked to the emergence and spread of human malignancies." (PMID 37529244, 2023). "Otherwise, several studies have proposed that LIMD2 correlates with the malignant progression of various types of cancer." (PMID 34724866, 2021). "Taken together, these results suggest that LIMD2 activates kinases that favor the trans-differentiation of the epithelial phenotype to a mesenchymal phenotype and promotes cancer metastasis in a cell dependent context." (PMID 33238381, 2020). "Whether there is a direct interaction between LIMD2 with specific binding sites on kinases in PTC cancer cells, which in turn trigger migration and invasion, needs to be determined." (PMID 33238381, 2020). "In this study, to interrogate the role of LIMD2 in cancer invasion and metastasis, we used CRISPR-mediated knockout (KO) of LIMD2 in PTC cells (BCPAP and TPC1)." (PMID 33238381, 2020). "It has also been observed that LIM domain-containing protein 2 (LIMD2), a LIM-domain only protein specifically expressed in metastatic lesions, directly binds the kinase domain of ILK and increases ILK activity, leading to increased migration and invasion by cancer cells." (PMID 35804980, 2022).
infection (1 paper, 2025). The state of being infected such as from the introduction of a foreign agent such as serum, vaccine, antigenic substance or organism. "Three novel genes—Limd2, Ptms, and Unc93b1—were also identified to correlate with MTB cellular infection." (PMID 39813329, 2025).
LIMD2 also shares sentences with these, for which no sentence is quoted: clear renal cell carcinoma (1 paper); esophageal cancer (1); fatty liver (1); Insulin resistance (1); liver disease (1); lymph node metastasis (1); melanoma (1); thyroid (1).